IGF1 (insulin like growth factor 1)
Diseases named in the same sentence as IGF1 in open-access papers (continued):
Sharing a sentence is not in itself a finding about the gene and the disease.
acromegaly (continued). "Herein, we present the case of a 56-year-old man with acromegaly, who had persistent elevated IGF-1 and initial suppressed GH value < 1 μg/L after OGTT." (PMID 37543629, 2023). "Although the guideline opposed monitoring GH and/or IGF-1 levels during pregnancy, a potential threat for acromegaly progression still exists." (PMID 37161564, 2023). "The aim of this review is to map the current literature regarding the state of the art regarding the impact of estrogens and SERMs on the GH/IGF1 axis, focusing on molecular pathways and the possible effects on acromegaly treatment." (PMID 37373068, 2023). "Acromegaly is characterized by GH and consequently IGF-1 hypersecretion, which occurs in adults, after conjugative cartilage welding." (PMID 37842314, 2023). "It is in agreement with other findings demonstrating reduced LA strain in active acromegaly, which was associated with systolic BP, NT-BNP, IGF-1, LA diastolic diameter, LV mass index, and global LV-LS." (PMID 37959322, 2023). "Estrogens were first used in acromegaly over 40 years ago, improving clinical symptoms and glucose metabolism and decreasing IGF1 by almost 50% of the starting values." (PMID 37373068, 2023). "Some decades ago, estrogens were first used to treat acromegaly, resulting in a significant decrease in IGF1 levels." (PMID 37373068, 2023). "This series suggests that adenomas of patients with gigantism secrete more GH and more IGF-1 levels than in patients with acromegaly." (PMID 36335516, 2023). "Augmentation index as a correlate of vascular stiffness was significantly increased in the patients with elevated IGF-1 and GH levels compared with the control group with controlled acromegaly." (PMID 36508085, 2023). "In the acromegaly cohort the median baseline GH and IGF-1/ULN were 7.9 (3.4–18.8) μg/L and 2.5 (1.8–3.4), respectively." (PMID 36525222, 2023). "After clinical suspicion, the diagnosis of acromegaly is based upon endocrine features (elevation IGF-1, unsuppressed GH during OGTT) and radiological confirmation of the adenoma in a pituitary magnetic resonance." (PMID 37373068, 2023). "Patients with acromegaly with active disease (aAP) presented with higher IGF-1 and GH levels compared patients with acromegaly with controlled disease (cAP) (P < 0.001)." (PMID 37670889, 2023). "The effect of the incongruence of GH and IGF-1 values on acromegaly comorbidities has been studied with discordant results on the onset or progression of the metabolic complications." (PMID 37829686, 2023). "Our study demonstrates higher prevalence of cardiovascular comorbidities in acromegaly patients and the impact of IGF-1 levels and body composition parameters in pathology in some of these comorbidities." (PMID 36309947, 2023). "The concentration of IGF-1 in patients with newly diagnosed acromegaly was similar to those treated with somatostatin analogs (SSA) due to incomplete transsphenoidal pituitary surgery." (PMID 37373574, 2023). "In this single-centre study, we show that following dose reduction of pasireotide over time, patients with acromegaly maintained their biochemical response (IGF1 < ULN) and had improved glycaemic control." (PMID 37530039, 2023). "More cancer screening should be considered when managing acromegaly, especially in patients with higher posttreatment GH and IGF-1." (PMID 37442901, 2023). "Patients with pituitary microadenomas or macroadenomas and elevated IGF-1 should be closely monitored for symptoms/signs of acromegaly and hypopituitarism." (PMID 37543629, 2023). "Rhythm disturbances includingatrial fibrillation are also more common in acromegaly patients compared to thegeneral population, as IGF-1 can directly affect myocardial contractility byincreasing intracellular Ca2+ levels." (PMID 39076279, 2023). "This subsequent disorder of hypersecretion of these stimulatory growth hormones, acromegaly, manifests as a product of the synergistic effects of tissue overgrowth produced by GH and IGF-1." (PMID 37755395, 2023).
acromegaly (continued). "Acromegaly is defined as an acquired dysmorphytic syndrome due to excessive secretion of growth hormone (GH) and consequently of insulin-like growth factor-1 (IGF-1)." (PMID 38465009, 2023). "IGF-1 measurement was selected by nearly all respondents in the 2021 survey and is currently recognised as the initial screening test for acromegaly." (PMID 36434293, 2023). "A cornerstone role is also posed in IGF-1 serum levels to monitor response to therapy and to define persistent vs controlled or cured acromegaly." (PMID 36973824, 2023). "Serum IGF-1 dosage is an effective screening method when clinical manifestations raise the suspicion of acromegaly." (PMID 37628857, 2023). "As the only FDA-approved oral octreotide capsule for long-term medical treatment of acromegaly, the Mycapssa® twice-daily oral capsule suggests a new opportunity for at-home long-term management of GH and IGF-1 levels in patients with acromegaly." (PMID 37755395, 2023). "Further, in vivo and in vitro research is required to fully understand how d3GHR impacts the concentrations of GH and IGF-1 as well as other metabolic markers in acromegaly." (PMID 37762211, 2023). "In the case-control section, patients with cancers diagnosed after acromegaly had a higher GH, IGF-1 and the disease-uncontrolled rate in the last visit." (PMID 37442901, 2023). "As we know, glucose metabolism disturbances in acromegaly are secondary to higher levels of GH and IGF-1." (PMID 37446150, 2023). "A statistical comparison of preoperative serum GH and IGF-1 levels in patients with gigantism and patients with acromegaly showed a significant elevation in the former." (PMID 36335516, 2023). "We consider the study of IGF-1 levels justified as a screening for acromegaly in patients with hyperprolactinemia and pituitary adenoma." (PMID 38796756, 2023). "Acromegaly, a chronic condition characterized by growth hormone (GH) and, in turn, insulin-like growth factor-1 (IGF-I) excess, is burdened by a series of systemic and metabolic comorbidities that strongly impair quality of life (QoL) and life expectancy." (PMID 37606222, 2023). "Hyperostosis is one of the most common manifestations of acromegaly, which results from GH and insulin-like growth factor-1 (IGF-1) overproduction." (PMID 36875488, 2023). "It is known that tumour SSTR2 expression in acromegaly correlates with lowering of serum IGF-1 and GH levels." (PMID 37851558, 2023). "Among the remaining seven patients, acromegaly was preliminarily confirmed on the base of the screening test—concentration of insulin-like growth factor 1 (IGF-1)—which was above the reference range." (PMID 37373574, 2023). "In acromegaly patients, myocardial hypertrophy occurs even inthe absence of hypertension and in young patients, emphasizing the direct impactof GH and IGF-1 in myocardial mechanics." (PMID 39076279, 2023). "Several comorbidities are related to chronic GH and/or IGF1 excess, such as cardiovascular, metabolic, osteoarticular and neoplastic complications, which increase the overall mortality of uncontrolled acromegaly." (PMID 37373068, 2023). "Acromegaly is a rare endocrine disease characterized by excessive release of growth hormone (GH) and insulin-like growth factor 1 (IGF-1), mainly due to GH-secreting pituitary adenomas." (PMID 38032888, 2023). "The diameter of not only the aorta but that of the main pulmonary artery was increased in acromegaly, and these changes were related to disease duration instead of serum hGH and IGF-1 level." (PMID 37959322, 2023). "Pegvisomant is a competitive inhibitor of the hGHR and in clinical trials was >90% effective in normalizing serum IGF1 in patients with acromegaly, despite a >20-fold reduction in hGHR-binding affinity compared to hGH or the hGH-G120K." (PMID 37442239, 2023). "Acromegaly can be diagnosed by measuring serum insulin-like growth factor-1 (IGF-1) and growth hormone (GH)." (PMID 37543629, 2023).
acromegaly (continued). "The use of tamoxifen in patients affected by acromegaly led to the reduction in IGF-1 in 82% of cases and the normalization of IGF-I in 47% of cases." (PMID 37958702, 2023). "In the cohort, similarly to the overall cancers, the most recent GH, IGF-1, and acromegaly-controlled rates were similar." (PMID 37442901, 2023). "On the other end of the spectrum, patients with increased serum GH and IGF-1 levels (acromegaly) have fewer circulating branched-chain amino acids (namely valine and isoleucine) and lysine compared to controls." (PMID 36837810, 2023). "AIM: Determining the proportion of patients with hyperprolactinemia and pituitary adenoma, who were examined for IGF-1 levels, and identifying the proportion of patients with acromegaly among this cohort." (PMID 38796756, 2023). "There were significant differences in the BMI, invasion of the cavernous sinus, GH, IGF-1, and prolactin levels at follow-up, occurrence of prolactin-secreting tumors, and recovery from acromegaly between the NTL and LTL groups after surgery." (PMID 37886642, 2023). "Acromegaly, a chronic metabolic disease, is characterized by the over-secretion of GH by pituitary adenomas, resulting in the increased release of IGF1 from the liver." (PMID 38203605, 2023). "In preclinical trials, this peptide has been shown to be effective in decreasing IGF1 levels, which shows its potential to develop a drug against acromegaly." (PMID 37513908, 2023). "Pegvisomant is a successful drug (marketed by Pfizer and prescribed for acromegaly) which acts as a competitive inhibitor/antagonist of endogenous hGH binding to the hGHR and normalizes serum IGF1 in >90% of the patients in clinical trials." (PMID 37442239, 2023). "In this article, we aim to present the relationship between GH, IGF-1, insulin signaling and glucose homeostasis and how acromegaly affects it." (PMID 36882643, 2023). "This prognosis has been mainly related to three different factors: the size and characteristics of the adenoma (71.4% invasive) and the increased GH and IGF-1 levels, statistically higher than those produced in acromegaly." (PMID 36335516, 2023). "A comparison between preoperative IGF-1 levels in 11 giants and IGF-1 levels in a population of 363 adults with acromegaly operated on at the same Center also demonstrates much higher levels of IGF-1 hypersecretion in giants, with statistical significance." (PMID 36335516, 2023). "Of the medical therapy options, the somatostatin analog class of drugs is the first line of medical therapy for acromegaly with clinical efficacy in managing GH levels, IGF-1 levels, and suppression of tumor growth." (PMID 37755395, 2023). "Acromegaly is the only disease with simultaneous elevation of circulating GH, IGF1 and insulin levels, and in which insulin resistance is associated with a reduction in body fat deposits, especially liver fat." (PMID 37842314, 2023). "Body mass index, invasion of the cavernous sinus, GH, IGF-1, and prolactin levels, the presence of a prolactin-secreting tumor, and recovery from acromegaly were significantly different (p < 0.05) in the NTL group and in the LTL group during the follow-up." (PMID 37886642, 2023). "Hyperphosphatemia and hypercalcemia in acromegaly patients are mediated by IGF-1’s direct effect on the Na-Pi cotransporter in the proximal convoluted tubules of the kidneys." (PMID 38137499, 2023). "Acromegaly diagnosis is established when plasma levels of IGF-1 are increased and the Oral Glucose Tolerance Test (OGTT) with 75gr of glucose can’t suppress Growth Hormone (GH) levels." (PMID 36973824, 2023). "Acromegaly is a multisystemic disease characterized by an excessive release of growth hormone (GH) and insulin-like growth factor-1." (PMID 37244996, 2023). "In this review, we analyze the state of the art concerning the impact of estrogen and SERMs on the GH/IGF1 axis, focusing on molecular pathways and the possible implications for acromegaly treatment." (PMID 37373068, 2023).
acromegaly (continued). "Pegvisomant (PEGV) is a brand-new GHR antagonist, which improves symptoms and maintains IGF-1 balance in acromegaly patients over the course of up to 12 weeks of treatment." (PMID 37762211, 2023). "Because of the modest efficacy of dopamine agonists in acromegaly, cabergoline monotherapy can be considered as first-line medical therapy only for those with modestly elevated GH and IGF-1 levels (IGF-1 < 2.5 × ULN)." (PMID 35090028, 2022). "A recent meta-analysis has been revealed that cabergoline single-agent therapy normalizes IGF-1 levels in more than one-third of acromegaly patients." (PMID 35612842, 2022). "Individuals with acromegaly, characterized by high circulating levels of GH and IGF1, also display concentric bi-ventricular hypertrophy with ensuing diastolic and systolic cardiac dysfunction." (PMID 35250583, 2022). "Acromegaly is a rare and slowly progressing disease derived from overproduction of GH and, consequently, IGF1, induced by a pituitary adenoma in most of the patients." (PMID 35612842, 2022). "In patients with acromegaly, sustained high levels of GH and IGF-1 stimulate the hearts and interacted with the GH and IGF-1 receptors, respectively, on the surface of cardiomyocytes." (PMID 36568107, 2022). "We also found that IGF-1-ULN was higher in patients with controlled acromegaly compared to the healthy controls, while GH levels were similar between these groups." (PMID 35340319, 2022). "The translation of these results to the clinic is feasible, given the availability of FDA-approved GHR antagonist Pegvisomant, which is currently approved for acromegaly and known to successfully normalize serum IGF1 in >90% of the patients." (PMID 35865483, 2022). "Acromegaly is defined by increased rate of growth hormone (GH) and insulin-like growth factor 1 (IGF1)." (PMID 35054115, 2022). "Acromegaly is a clinical syndrome characterized by growth hormone (GH) and insulin-like growth factor-1 (IGF-1) excess." (PMID 35922724, 2022). "The results of this study provided evidence of the chronic effects of excessive GH and IGF-1 on human skin under a magnifying view and implied the reversibility of acromegaly-related skin presentations upon withdrawal of GH/IGF-1 hypersecretion." (PMID 36818464, 2022). "Excessive growth hormone and insulin-like growth factor 1 contribute to cutaneous changes in acromegaly." (PMID 36818464, 2022). "A significant intergroup difference was higher GH (8.05 ± 16.18 vs. 0.78 ± 1.25 ng/mL) and IGF-1 (547.0 ± 342.1 vs. 146.7 ± 51.4 ng/mL) levels in patients with acromegaly." (PMID 35248150, 2022). "GH and IGF-1 excess are strongly related to the development of cardiovascular complications, especially in patients with active acromegaly but frequently persist after adequate treatment in patients with the controlled disease." (PMID 36326330, 2022). "Our group previously reported that SST2 IRS correlated with the age-adjusted IGF-1 levels after fg-SRL therapy in the cohort of acromegaly patients we analyzed by DIA in the present study." (PMID 35895707, 2022). "Therapeutic goals in patients with acromegaly are the biochemical control of GH and IGF-1 secretion, the control of systemic comorbidities, the reduction of mortality, and the restoration of QoL." (PMID 35207363, 2022). "Excessive growth in mandibular condyles is one of the general radiographic and clinical findings of acromegaly Beside its important role in the human growth and development, IGF-1 has also regulatory effect on the activity of growth plate." (PMID 35717618, 2022). "To date, GH (a direct product of the adenoma) and IGF-1 (mainly produced in the liver upon GH stimulus) are the classical biochemical markers of disease activity in acromegaly." (PMID 36042253, 2022). "In in vitro experiments, the knockdown of EIF2β changed the phenotype of somatotroph adenomas, including cell proliferation, migration, and the secretion ability of growth hormone/insulin-like growth factor-1." (PMID 36361871, 2022).
acromegaly (continued). "It is known that in acromegaly the increased secretion of the GH and the IGF-1 leads to increased bone turnover." (PMID 35528019, 2022). "Upon reduction of serum levels of GH and IGF-1 after treatment, according to previous publications, reversibility of acromegaly-related skin lesions assessed by unaided eyes varied." (PMID 36818464, 2022). "Currently, only IGF-1 and GH blood values are recommended for acromegaly to detect possible disease activity and to evaluate treatment outcomes or possible complications during the follow-up period." (PMID 35685582, 2022). "The literature on the general psychological assessment and specific psychopathological conditions in acromegaly is still limited, and the interplay between GH and IGF1 excess and psychological discomfort is yet to be clarified." (PMID 36165745, 2022). "The most frequent phenotype in newly diagnosed acromegaly in the elderly includes small adenomas and moderately high IGF-1 levels." (PMID 36187107, 2022). "Another potential limitation is the heterogeneity of the acromegaly group, since we had patients with disease duration ranging from 9 to 18 years and IGF-1 levels ranging from 1.04 to 2.54 times the upper limit of normal range." (PMID 35185796, 2022). "Improvements in diagnostic modalities have increased the prevalence of somatotroph adenomas through the identification of active acromegaly (high IGF-1 and/or GH levels) in clinically asymptomatic patients, also called silent somatotroph adenomas." (PMID 36361871, 2022). "The course of the acromegaly continues with periosteal new bone production due to the excessive levels of GH and IGF-1 leads to growth of skeletal system." (PMID 35717618, 2022). "First, during active acromegaly, when patients are exposed to supraphysiological GH and IGF-1 levels, there is increased endocortical turnover in the presence of an increased number of bone remodeling sites, but stable trabecular bone mass." (PMID 34448099, 2022). "In the present study we demonstrated preservation of muscle mass despite a fall in serum GH/IGF-1 concentrations with disease control in patients with acromegaly." (PMID 35663315, 2022). "Acromegaly is a rare disorder resulting from excessive growth hormone production (GH) and serum insulin like growth factor-1 (IGF-1) concentrations." (PMID 36326330, 2022). "Increased IGF-1 values in acromegaly probably affect the viscoelastic properties of the cornea by increasing CH and CRF." (PMID 36431227, 2022). "Serum insulin-like growth factor-1 was 340 nmol/L (RI: 12-92), and CT scan revealed a hypophyseal mass, and a presumptive diagnosis of acromegaly was made." (PMID 35923821, 2022). "Acromegaly is a rare disease characterized by increased growth hormone (GH) and insulin-like growth factor 1 (IGF-1)." (PMID 35340319, 2022). "Once elevated GH and IGF-1 levels confirm acromegaly, a high-resolution magnetic resonance image (MRI) should be obtained to inspect the pituitary gland for an adenoma." (PMID 35992136, 2022). "The results of Bulgarian Acromegaly Database have revealed that cabergoline monotherapy normalizes IGF-1 levels in more than one-third of acromegaly patients, however, better remission rate was observed in previously irradiated patients." (PMID 35612842, 2022). "Patients with acromegaly have an increased amount of extracellular fluid, which is related to the sodium-retaining effect of GH/IGF-1." (PMID 36431227, 2022). "Until now, high levels of GH and IGF-1, the persistence of active acromegaly despite therapies, the untreated hypogonadism, the overtreated central hypoadrenalism were recognized as risk factors for skeletal fragility in acromegaly." (PMID 35922724, 2022). "Continuous stimulation from the hypersecretion of GH and IGF-1 results in acromegaly with a series of clinical presentations, including facial appearance changes, extremity enlargement, bone modifications, and systemic complications." (PMID 36818464, 2022).